PRDX3 (peroxiredoxin 3)
Diseases named in the same sentence as PRDX3 in open-access papers (continued):
Sharing a sentence is not in itself a finding about the gene and the disease.
sarcopenia (2 papers, 2022 to 2025). Progressive decline in muscle mass due to aging which results in decreased functional capacity of muscles. "To test whether scavenging hydrogen peroxide from skeletal muscle mitochondria can rescue phenotypes associated with sarcopenia, we generated mice that constitutively express human peroxiredoxin 3 in skeletal muscle (mPRDX3Tg mice)." (PMID 35199907, 2022). "Overall, the results of our study indicate the significance of mitochondrial hydrogen peroxide and PRDX3 in sarcopenia, which can help narrow our targets for drug development of sarcopenia." (PMID 35199907, 2022). "Muscle‐specific overexpression of Prdx3 in Sod1KO mice allows us to directly investigate the therapeutic potential of scavenging the mitochondrial hydrogen peroxide in redox‐dependent sarcopenia." (PMID 35199907, 2022). "In conclusion, our data demonstrate that increased expression of PRDX3 in skeletal muscle normalized the excess mitochondrial hydrogen peroxide generation in a redox‐dependent sarcopenia." (PMID 35199907, 2022). "Our findings demonstrate that muscle‐specific PRDX3 overexpression reduces mitochondrial H2O2 generation, improves mitochondrial function, and mitigates loss of muscle quantity and quality, despite persisting NMJ impairment in a murine model of redox‐dependent sarcopenia." (PMID 35199907, 2022).
serous ovarian cancer (2 papers, 2018 to 2019). "Furthermore, PRDX3 played significant prognostic roles, particularly in poor differentiation and late-stage serous ovarian cancer patients." (PMID 30104402, 2018).
thymoma (2 papers, 2016 to 2019). A neoplasm arising from the epithelial cells of the thymus. "However, it was also demonstrated that overexpression of PRDX3 in thymoma cells resulted in decreased cell proliferation." (PMID 27958341, 2016).
triple-negative breast carcinoma (2 papers, 2024 to 2025). An invasive breast carcinoma which is negative for expression of estrogen receptor (ER), progesterone receptor (PR), and human epidermal growth factor receptor 2 (HER2). "In triple-negative breast cancer, PRDX3 regulates tumor metastasis via ERK signaling-mediated MMP-1 expression." (PMID 41049446, 2025). "PRDX3 overexpression promoted cancer cell migration and invasion, while depletion of PRDX3 reversed this phenomenon in triple negative breast cancer cells in vitro." (PMID 38321552, 2024). "We show that shRNA-mediated gene silencing of PRDX3 inhibits cell migration and invasion in two triple-negative breast cancer cell lines." (PMID 38321552, 2024).
amyloidosis (1 paper, 2020). A disorder characterized by the localized or diffuse accumulation of amyloid protein in various anatomic sites. "We also profiled CSF in the 5xFAD mouse model to validate amyloidosis-induced changes, and found consistent mitochondrial decreases (SOD2, PRDX3, ALDH6A1, ETFB, HADHA, and CYB5R3) in both human and mouse samples." (PMID 32711556, 2020).
atherosclerosis (1 paper, 2021). A disease characterized by the build-up of fatty material and calcium deposition in the arterial wall resulting in partial or complete occlusion of the arterial lumen. "Nonetheless, recent studies have implicated potential roles of Prdx3 in various cell types associated with atherosclerosis." (PMID 34439492, 2021). "Although alterations to the expression of Prdx3 in mitophagy appear to be relevant, current data are insufficient to identify potential mechanisms in atherosclerosis." (PMID 34439492, 2021). "However, a possible mechanism of Prdx3 in atherosclerosis may be associated with mitophagy." (PMID 34439492, 2021). "Although several studies have reported the protective roles of Prdx isoforms against atherosclerosis, the role of Prdx3 in the pathogenesis of atherosclerosis remains unclear." (PMID 34439492, 2021).
cardiac hypertrophy (1 paper, 2025). "PRDX3 overexpression prevents cardiac hypertrophy and HF by reducing oxidative stress and restoring mitochondrial function." (PMID 40646297, 2025).
Cerebellar hypoplasia (1 paper, 2023). Cerebellar hypoplasia is a descriptive term implying a cerebellum with a reduced volume, but a normal shape and is stable over time.
cervical intraepithelial neoplasia (1 paper, 2025). "Moreover, PRDX3 was found to take part in the formation of cervical intraepithelial neoplasia (CIN), where PRDX3 helped HPV persistent infection transform into CIN, and the PRDX3 expression level increased along as the grade of CIN progressed." (PMID 41049446, 2025).
colon adenocarcinoma (1 paper, 2023). "In colon adenocarcinomas, stem cells have been reported to use mitochondrial OXPHOS to produce ATP and maintain mitochondrial function via the FOXM1/PRDX3 pathway, thereby maintaining their survival and stem-cell characteristics." (PMID 36844874, 2023).
diabetic nephropathy (1 paper, 2025). "The SGLT2 inhibitor empagliflozin has been shown to alleviate diabetic nephropathy by restoring the expression of peroxiredoxin 3 (Prdx3) and reducing the levels of ROS and mitochondrial ROS in a diabetic (db/db) mouse model." (PMID 41074478, 2025).
Duchenne muscular dystrophy (1 paper, 2025). Duchenne muscular dystrophy (DMD) is a neuromuscular disease characterized by rapidly progressive muscle weakness and wasting due to degeneration of skeletal, smooth and cardiac muscle. "Prdx3 and Prdx5 levels also showed a decreasing trend in mouse models of Duchenne muscular dystrophy (DMD) and dysferlinopathy‐associated accelerated muscle degeneration." (PMID 41147088, 2025).
dyslipidemia (1 paper, 2016). "Expression of Sod2, Txr1, Prdx3 and Gpx1 was altered by 3 months of exercise and/or severe dyslipidemia in 6-mo dyslipidemic mice." (PMID 27010651, 2016).
Hepatic steatosis (1 paper, 2021). Steatosis is a term used to denote lipid accumulation within hepatocytes. "Glrx-deficient mice spontaneously develop hepatic steatosis, whereas Prdx3 overexpression in mitochondria is able to effectively decrease cellular ROS." (PMID 34572415, 2021).
laryngeal squamous cell carcinoma (1 paper, 2017). A squamous cell carcinoma that arises from the larynx. "This study examined the expression profile of PRDX3 and its possible clinical value in laryngeal squamous cell carcinoma (LSCC)." (PMID 27966448, 2017).
laryngeal tumor (1 paper, 2017). "We selected the laryngeal tumor cell line Hep-2 to perform in vitro functional analyses by constructing knockdown vectors of PRDX3." (PMID 27966448, 2017). "Compared to the normal tissues, PRDX3 was dramatically up-regulated in the laryngeal tumor tissues." (PMID 27966448, 2017).
liver disease (1 paper, 2021). "Peroxiredoxin 3 (PRX3) plays a crucial role in scavenging reactive oxygen species (ROS), but its hepatoprotective capacity in acetaminophen (APAP)-induced liver disease remains unclear." (PMID 34054813, 2021).
lung adenocarcinoma (1 paper, 2016). A carcinoma that arises from the lung and is characterized by the presence of malignant glandular epithelial cells. "In this study, we found the expression of Dachshund 1 (DACH1) is downregulated while peroxiredoxin 3 (PRX3) upregulated in both lung adenocarcinoma tissues and cells." (PMID 26810067, 2016).
lymphoma (1 paper, 2016). A malignant (clonal) proliferation of B- lymphocytes or T- lymphocytes which involves the lymph nodes, bone marrow and/or extranodal sites. "Interestingly, downregulation of TRX inhibitory protein VDUP1, and upregulation of PRDX3 and PRDX4, correlated with poor prognosis of DLBCL patients, indicating tumor-promoting role of TRX-like enzymes in lymphomas." (PMID 26636537, 2016).
metastatic disease (1 paper, 2021). "A significant strong correlation between high PRDX3 expression and metastatic disease development and reduced OS was demonstrated, proposing that high PRDX3 expression in UM is also a marker of poor prognosis." (PMID 35008260, 2021).
non-small cell lung carcinoma (1 paper, 2025). A group of at least three distinct histological types of lung cancer, including non-small cell squamous cell carcinoma, adenocarcinoma, and large cell carcinoma. "In non-small cell lung cancer, suppression of PRDX3 induced by a ubiquitin specific peptidase-7 (USP7)-mediated manner could mitigate intracellular ROS and promote Osimertinib resistance." (PMID 41049446, 2025).
pancreatic adenocarcinoma (1 paper, 2017). "In addition, a recent report suggests that PRDX3 is associated with tumor suppressor functions in pancreatic adenocarcinoma as its strong expression correlates with smaller tumor size, reduced invasion and negative nodal status." (PMID 28994702, 2017).
pancreatitis (1 paper, 2020). Inflammation of the pancreas. "As expected, PGC-1α deficiency triggered the down-regulation of Sod2 and Prdx3 under basal conditions and during pancreatitis." (PMID 32961723, 2020).
pulmonary fibrosis (1 paper, 2024). Chronic progressive interstitial lung disorder characterized by the replacement of the lung tissue by connective tissue, leading to progressive dyspnea, respiratory failure, or right heart failure. "The effect of YAP1 on AT2 cells during pulmonary fibrosis depended on the modulation of cellular senescence and mitochondrial function mediated through targeting of Prdx3." (PMID 38945958, 2024). "In summary, Prdx3 inhibits pulmonary fibrosis by alleviating senescence and mitochondrial dysfunction in the lungs." (PMID 38945958, 2024). "Overexpression of Prdx3 suppressed experimental pulmonary fibrosis, whereas silencing Prdx3 partially abrogated the protective effect of YAP1." (PMID 38945958, 2024). "In conclusion, this study demonstrated that YAP1 alleviates lung injury and pulmonary fibrosis by regulating Prdx3 expression to improve mitochondrial dysfunction and block senescence in AT2 cells, revealing a potential novel therapeutic strategy for pulmonary fibrosis." (PMID 38945958, 2024). "We next investigated whether the overexpression of Prdx3 prevents pulmonary fibrosis in mice." (PMID 38945958, 2024). "Pulmonary function tests and micro-CT analysis demonstrated that Prdx3 silencing increased pulmonary fibrosis in BLM-treated YAP1-cKI mice, indicating that YAP1 inhibited BLM-induced pulmonary fibrosis through Prdx3 in vivo." (PMID 38945958, 2024). "In this study, we first revealed that increased expression of YAP1 in AT2 cells mitigated BLM-induced pulmonary fibrosis and revealed the regulatory relationship between YAP1/TEAD1 and Prdx3." (PMID 38945958, 2024). "Silencing of Prdx3 abolished the beneficial effects of YAP1, indicating the vital role of the YAP1/TEAD1-Prdx3 axis in inhibiting cellular senescence and maintaining cell survival, whereas overexpression of Prdx3 in AT2 cells alleviated pulmonary fibrosis." (PMID 38945958, 2024).
spinocerebellar ataxia type 32 (1 paper, 2025). Spinocerebellar ataxia type 32 (SCA32) is a subtype of autosomal dominant cerebellar ataxia type 1 (ADCA type 1) characterized by ataxia, cognitive impairment and azoospermia in males. "Spinocerebellar ataxia type 32 (SCAR32) is a rare autosomal neurodegenerative disorder caused by mutations in the peroxiredoxin 3 (PRDX3) gene, which encodes a mitochondria-specific antioxidant enzyme critical for maintaining cellular redox homeostasis." (PMID 41351775, 2025).
thyroid (1 paper, 2025). "Although thyroid autoimmunity and gland enlargement were observed, a causal association between PRDX3 deficiency and thyroid pathology should be further studied." (PMID 41351775, 2025).
transient cerebral ischemia (1 paper, 2016). "In the brain, expression of Prdx3 increased following transient cerebral ischemia, while intraventricular administration of Prx3 significantly reduced ischemic damage, lipid peroxidation and the release of cytochrome c." (PMID 26501408, 2016).
uveitis (1 paper, 2025). An inflammatory process affecting a part of or the entire uvea. "Our previous research demonstrated that ICA alleviated uveitis by targeting peroxiredoxin 3 to regulate the polarization of retinal microglial cells toward the M1/M2 phenotype." (PMID 40620905, 2025).
cancer (45 papers, 2007 to 2026). A tumor composed of atypical neoplastic, often pleomorphic cells that invade other tissues. "To confirm the cancer-promoting biological function of PRDX3 in LNM of CCa, we conducted loss-of-function and gain-of-function assays in CCa cell lines." (PMID 41049446, 2025). "Taken together, these studies demonstrate the important role of Prdx3 in hypoxia, which is associated with cancer development and the response to cancer therapies." (PMID 31500275, 2019). "This implies that the differential response of Prdx3 expression is regulated by diverse signaling pathways that are associated with cancer progression." (PMID 31500275, 2019). "Prdx3 knock out mice have shown a reduction in tumor volume and metastasis giving a clue for association of Prdx3 with FOXM1 associated pathways for cancer development." (PMID 31500275, 2019). "Our survey of studies analyzing the expression of Prdx3 in human cancers clearly shows that Prdx3 is upregulated in many cancers and it is associated with cell proliferation." (PMID 31500275, 2019). "Our results showed linear, up-regulation of Prdx3 and Gpx1 in the middle section of small intestine; this can activate antioxidant processes that are relevant for bacteria-associated inflammation, cancer-promoting conditions and tumor progression." (PMID 26861690, 2016). "Regions statistically significantly associated with CIN3/cancer included genes for peroxiredoxin 3 PRDX3, and ribosomal protein S19 RPS19." (PMID 22496757, 2012). "The single most significant SNPs from each gene associated with CIN3/cancer were PRDX3 rs7082598 (Ptrend<0.0001), and RPS19 rs2305809 (Ptrend=0.0007), respectively." (PMID 22496757, 2012). "Moreover, Prdx3 and Prdx2 have been associated with cancer aggressiveness and patient survival, and higher Prdx2 and Prdx3 expressions were associated with less aggressiveness and longer survival." (PMID 33425206, 2020). "The upregulated expression of Prdx3 and Prdx5 is associated with the development of chemoresistance in different cancers and selective targeting of these mitochondrial Prdxs can lead to sensitization of cancer cells to chemotherapy." (PMID 31500275, 2019). "However, an increased production of Prdx3 and Prdx5 is associated with the development of chemoresistance in certain types of cancers and it leads to further complications in cancer treatment." (PMID 31500275, 2019). "PRDX3 was differentially expressed in cancers, and its expression appeared to be influenced by copy number variation and methylation status." (PMID 41838687, 2026). "Peroxiredoxin 3 (PRDX3), a key mitochondrial redox enzyme, has been implicated in malignant tumor initiation and development." (PMID 41838687, 2026). "The anti-cancer action of Thio is also mediated by the formation of covalent adducts with cysteine residues in the mitochondrial protein peroxiredoxin 3 (PRDX3), an antioxidant enzyme that is frequently upregulated in cancers." (PMID 40867592, 2025). "Similar to cancer cells, although PRDX3 is upregulated after schistosome infection, the tissue still exhibits significantly high levels of ROS." (PMID 40462224, 2025). "Overexpression of PRDX3 has been documented in a number of cancer types due to alteration of the metabolic state in mitochondria." (PMID 38321552, 2024). "Reciprocal experiments show that PRDX3 overexpression promotes invasion and migration of the cancer cells, processes which are important in the metastatic cascade." (PMID 38321552, 2024). "These intriguing observations, derived from experiments conducted across multiple cancer cell lines, pointed to hyperoxidized PRDX3 as a potential specific marker for ferroptosis." (PMID 38179338, 2023). "The authors also showed that deletion of PRDX3 confers heightened resistance to ferroptosis in cancer cells triggered by erastin, a well-established FIN known for its mode of action in blocking cystine uptake." (PMID 38179338, 2023).